RIC1 (RIC1 partner of RAB6A GEF complex)
Description:
The RIC1-RGP1 complex acts as a guanine nucleotide exchange factor (GEF), which activates RAB6A by exchanging bound GDP for free GTP, and may thereby be required for efficient fusion of endosome-derived vesicles with the Golgi compartment. The RIC1-RGP1 complex participates in the recycling of mannose-6-phosphate receptors. Required for phosphorylation and localization of GJA1. Is a regulator of procollagen transport and secretion, and is required for correct cartilage morphogenesis and development of the craniofacial skeleton.
Synonyms: CIP150; KIAA1432; bA207C16.1; CATIFA
Tractability: PROTAC: ubiquitination databases record sites on it.
Gene: Protein-coding gene on chromosome 9 (5,629,025 to 5,776,557, forward strand). Ensembl gene ENSG00000107036.
Subcellular location: Cytoplasm, cytosol; Membrane
Pathways (Reactome):
Vesicle-mediated transport: Intra-Golgi traffic; RAB GEFs exchange GTP for GDP on RABs; Retrograde transport at the Trans-Golgi-Network
Gene Ontology:
Molecular function: guanyl-nucleotide exchange factor activity; protein binding; small GTPase binding
Biological process: cranial skeletal system development; negative regulation of protein catabolic process; positive regulation of GTPase activity; regulation of extracellular matrix constituent secretion; retrograde transport, endosome to Golgi; intracellular protein transport
Cellular component: cytosol; membrane; protein-containing complex; Ric1-Rgp1 guanyl-nucleotide exchange factor complex; Golgi membrane; trans-Golgi network membrane
Genetic constraint (gnomAD): Loss-of-function variants: 62 observed, 132.77 expected, observed/expected ratio (o/e) 0.47, 90% interval 0.38 to 0.58. The synonymous counts are far from expectation, so gnomAD's model fits this gene poorly and the ratio says little. Missense variants: 1,577 observed, 1,533.2 expected, observed/expected ratio (o/e) 1.03, 90% interval 0.99 to 1.07. Synonymous variants: 674 observed, 547.58 expected, observed/expected ratio (o/e) 1.23, 90% interval 1.15 to 1.31.
Homologues: Orthologues: chimpanzee RIC1 (99% identical), macaque RIC1 (99% identical), pig RIC1 (96% identical), rabbit RIC1 (96% identical), guinea pig RIC1 (93% identical), mouse Ric1 (93% identical), dog RIC1 (92% identical), rat Ric1 (92% identical), tropical clawed frog ric1 (79% identical), zebrafish RIC1 (62% identical), Drosophila melanogaster Rich (34% identical), Caenorhabditis elegans R06F6.8 (29% identical).
Diseases named in the same sentence as RIC1 in open-access papers:
RIC1 is named in the same sentence as 21 diseases in open-access papers, as found by Europe PMC text mining. Sharing a sentence is not in itself a finding about the gene and the disease. The quoted sentences say what the papers report.
cleft lip (2 papers, 2022). Congenital defect in the upper lip where the maxillary prominence fails to merge with the merged medial nasal prominences. "Mutations in RIC-1, a subunit of the Golgi-localized guanine nucleotide exchange factor (GEF) for RAB6A, cause CATIFA (cleft lip, cataract, tooth abnormality, intellectual disability, facial dysmorphism, attention-deficit hyperactivity disorder) syndrome." (PMID 35023559, 2022).
scoliosis (1 paper, 2023). A congenital or acquired spinal deformity characterized by lateral curvature of the spine. "Deficiencies of RIC1 in CATIFA and Rgp1 in zebrafish models are consistent with type II collagenopathies, affecting collagen II secretion, and their common presentation includes scoliosis, cleft palate and a shorter jaw." (PMID 36843607, 2023).
neurodegenerative disease (1 paper, 2024). A disorder of the central nervous system characterized by gradual and progressive loss of neural tissue and neurologic function. "Mutations in either RIC1 or subunits of the GARP complex have been associated with neurodegenerative disease in the human population." (PMID 38645119, 2024).
RIC1 also shares sentences with these, for which no sentence is quoted: breast carcinoma (3 papers); cancer (2); Intellectual disability (2); amyotrophic lateral sclerosis (1); attention deficit-hyperactivity disorder (1); bacterial infections (1); Catifa syndrome (1); cholangiocarcinoma (1); dementia (1); diphtheria (1); endometrial cancer (1); infant botulism (1); lung carcinoma (1); Parkinson disease (1); primary bone cancer (1); tetanus (1); tumor (1); type II collagenopathies (1).